INS (insulin)
Diseases named in the same sentence as INS in open-access papers (continued):
Sharing a sentence is not in itself a finding about the gene and the disease.
Hyperglycemia (continued). "By increasing insulin sensitivity in the liver and peripheral tissues and reducing gluconeogenesis, metformin decreases hyperglycemia and compensatory β-cell hyperinsulinemia." (PMID 40149685, 2025). "The STZ-NA model used in this study closely mimics human T2DM by inducing moderate hyperglycemia, β-cell dysfunction, and reduced insulin sensitivity." (PMID 41227734, 2025). "The low glucose threshold when insulin delivery is stopped can be set between 3.3 and 4.7 mmol/l and the algorithm hyperglycaemia threshold is 10.0 mmol/l." (PMID 39653802, 2025). "A marked and sustained elevation of their levels during CIPII has been reported, associated with the formation of immunogenic aggregates with a possible delay in insulin action and hyperglycemia, especially postprandial, or unpredictable hypoglycemia." (PMID 40995084, 2025). "The adverse effects of a high-fat diet, galactose, and oxidative stress have been recognized in relation to insulin secretion and insulin sensitization, which can lead to hyperglycemia." (PMID 41462653, 2025). "It is characterized by hyperglycemia that results from defects in insulin secretion, insulin action, or both." (PMID 40995268, 2025). "Probands 1 and 2 in our study had hyperglycaemia on the first and third day of life, respectively, which required insulin treatment." (PMID 40062559, 2025). "When overactive, PKC isoforms contribute to insulin resistance, reducing the cells’ efficiency in responding to insulin and taking up glucose, further exacerbating hyperglycemia." (PMID 40280905, 2025). "In conclusion, hyperglycemia, IR, abnormal insulin secretion from pancreatic β-cells, and glucose metabolic disturbances are closely interrelated and interact synergistically to exacerbate disease severity in AP." (PMID 40937420, 2025). "Hyperglycemia is thought to influence protein levels through a suboptimal insulin dynamic, as described in an animal study." (PMID 40071794, 2025). "These occurrences drive β-cell dysfunction, characterised by impaired insulin secretion and reduced β-cell mass, further exacerbating hyperglycaemia and metabolic dysfunction." (PMID 39982365, 2025). "The option to delay the hyperglycemia alert has been shown in some studies to reduce the incidence of hypoglycemia due to overcorrection by avoiding unnecessary insulin administration." (PMID 41462808, 2025). "Inflammatory cytokines profoundly disrupt insulin signaling and exacerbate metabolic dysfunction, leading to a more complex and dynamic pattern of stress hyperglycemia in sepsis compared with other critical illnesses." (PMID 41585235, 2025). "Hyperglycemia, lipid metabolism disorders, and abnormalities in the insulin signaling pathway are widely recognized as the initiating factors underlying various pathophysiological changes in DRN." (PMID 40536048, 2025). "Corticosteroids, often administered for severe COVID-19, can exacerbate hyperglycemia and increase insulin requirements, potentially offsetting the glycemic benefits of DPP-4 inhibitors." (PMID 40869643, 2025). "Molecular disruptions in skeletal muscle can impair insulin signalling, reducing glucose uptake efficiency and leading to hyperglycemia." (PMID 40329491, 2025). "The patient had been diagnosed with T1DM since childhood, struggling to control his hyperglycemia despite high doses of insulin." (PMID 40144769, 2025). "In contrast, patients with GCK-hyperglycemia required significantly higher insulin doses — particularly in the second trimester — yet achieved poorer glycemic control." (PMID 41409604, 2025). "As β-cells fail, insulin secretion declines, exacerbating hyperglycemia and metabolic stress, which in turn activates more immune cells and inflammatory pathways." (PMID 40689212, 2025). "As with insulin, incretin hormones are secreted after nutrient intake and, together with hyperglycemia, stimulate insulin secretion." (PMID 40362870, 2025).
Hyperglycemia (continued). "Studies have shown that long-term chronic adipsin supplementation in db/db mice ameliorates hyperglycemia and increases plasma insulin concentration while preserving beta cells." (PMID 40564980, 2025). "Secondary outcomes included length of hospital stay and rebound hyperglycemia, defined as a glucose measure of > 180 mg/dL in the six hours after the insulin drip was stopped." (PMID 40978981, 2025). "Pancreatic β‐cells secrete insulin to facilitate glucose uptake in insulin‐sensitive tissues such as skeletal muscle, thereby maintaining glucose homeostasis and preventing hyperglycemia or hypoglycemia." (PMID 41190649, 2025). "Early in the disease, beta cells compensate by increasing insulin production, preventing hyperglycemia." (PMID 40722684, 2025). "The reduction in insulin signaling in combination with hyperglycemia decreases sXBP-1 and concurrently increases CHOP expression, impairing adaptive sXBP-1 signaling and causing maladaptive ER stress in podocytes." (PMID 40027018, 2025). "This pattern underscores the need for targeted insulin therapies, particularly in subtypes where hyperglycemia is more pronounced." (PMID 40562310, 2025). "Hyperglycemia is regarded as an on-target effect of PI3K inhibitors and is linked to the critical role of the PI3K pathway in insulin signaling and glucose homeostasis." (PMID 40041495, 2025). "In the liver specifically, β2-adrenergic stimulation promotes potassium uptake both directly—via enhanced Na+/K+-ATPase activity—and indirectly, through glycogenolysis-induced hyperglycemia and subsequent insulin release." (PMID 40507597, 2025). "He had rapid hyperglycemia correction with IV fluids alone; IV insulin (starting rate 0.05 units/kg/h) was added ~24 h after arrival to the hospital and titrated up to a maximal rate of 0.23 units/kg/h." (PMID 40612706, 2025). "ROS from hyperglycemia can also impair insulin-stimulated nitric oxide production by affecting the activation of the IRS-1-mediated PI 3-kinase/AKT pathway." (PMID 40871683, 2025). "IR is marked by a diminished tissue response to insulin, which exacerbates hyperglycaemia through unsuppressed hepatic gluconeogenesis and decreased muscular glucose uptake, requiring intensification of exogenous insulin therapy." (PMID 40130476, 2025). "As the nutritional intake was gradually increased, corresponding preemptive adjustments to the insulin infusion rate (15% increases on the second and third days) were made to match the increased glucose load and prevent hyperglycemia." (PMID 39931500, 2025). "IR, characterized by reduced target tissue sensitivity to insulin and consequent uncontrolled hyperglycemia, is a key link between VAT accumulation and DKD." (PMID 41393943, 2025). "Our patient was a strong candidate for GH, given her marked hyperglycemia and overzealous, exclusive use of short-acting insulin." (PMID 40370476, 2025). "In vivo studies have shown that CBD reduces hyperglycemia and increases plasma insulin levels at doses ranging from 5 mg/kg to 30 mg/kg." (PMID 40283884, 2025). "Significantly, skeletal muscle serves as a crucial target for managing hyperglycemia, accounting for roughly 80% of postprandial insulin-mediated glucose absorption and is essential for maintaining glucose equilibrium." (PMID 39995417, 2025). "Dysfunction of β-cells leads to insufficient insulin secretion, resulting in hyperglycemia and metabolic disturbances." (PMID 40166045, 2025). "Further, our participants’ experiences align with the suggestion from the National Athletic Trainers’ Association regarding consulting physicians for increased basal rates or small insulin boluses during periods of exercise-induced hyperglycemia." (PMID 39823464, 2025). "The hyperglycemia induced by PI3Ki can lead to compensatory increases in insulin secretion, which have been shown to reactivate the PI3K/AKT signaling pathway within tumor cells, potentially inducing resistance to therapy." (PMID 40573322, 2025).
Hyperglycemia (continued). "DM comprises a group of metabolic disorders characterized by chronic hyperglycemia resulting from impaired insulin secretion, insulin action, or both." (PMID 41012437, 2025). "This likely reflects the fact that insulin was used to treat hyperglycemia and was carefully dosed to avoid hypoglycemic events, suggesting appropriate insulin dosing practices." (PMID 40150028, 2025). "Chronic treatment with AUY922 in db/db homozygous mice reversed hyperglycemia, while in diet-induced obese mice, it enhanced insulin sensitivity." (PMID 41226319, 2025). "In contrast, hexanoic acid improved both hyperinsulinemia and hyperglycemia and increased insulin sensitivity and plasma GLP-1 levels." (PMID 40944255, 2025). "The significance of insulin dose per day and hyperglycemia in coronary artery disease morbidity and mortality was investigated in nonobese T1D individuals followed for 18 years." (PMID 39998445, 2025). "This treatment was more effective as compared to insulin reduction in avoiding exercise—induced hypoglycemia and avoided significant hyperglycemia noted with 40 mg dose of oral glucose (OG) whilst being as effective in hypoglycemia prevention." (PMID 40364253, 2025). "Ghrelin, produced and secreted in the stomach, stimulates appetite by acting on the hypothalamus and inhibits insulin secretion, leading to hyperglycemia." (PMID 41195415, 2025). "Clinically, SGLT2 inhibitors have demonstrated the potential to rapidly improve hyperglycemia and reduce the required insulin dose, particularly in patients with treatment‐resistant hyperglycemia." (PMID 40828947, 2025). "Subcutaneous injection of insulin decreased the blood glucose level to 12.2 ± 1.0% after 1 h, however the levels returned to hyperglycemia after 4 h." (PMID 39815320, 2025). "Medical nutrition therapy is foundational to overall PBH management with the purpose of reducing nutrient-induced hyperglycemia, which stimulates robust insulin secretion." (PMID 40648766, 2025). "STZ depletes pancreatic β cells, thereby lowering systemic insulin levels and severely disrupting glucose homeostasis as indicated by sustained hyperglycemia after an intraperitoneally injected glucose load." (PMID 40371988, 2025). "GLP-1 is released after nutrient intake and acts in conjunction with hyperglycemia in a synergistic way to stimulate insulin secretion." (PMID 40380290, 2025). "Intravenous insulin therapy is commonly used in severe cases of AP, as these patients often have significant hyperglycemia and require rapid and precise glycemic control." (PMID 40937420, 2025). "A key observation in the data above is that hyperglycemia develops early in SCD mice before reductions in fasting serum insulin." (PMID 40294908, 2025). "It is important to keep in mind that the mechanism of action of glibenclamide is not only to reduce hyperglycemia by stimulating insulin secretion but this drug also has hypoglycemia as a side effect." (PMID 40649331, 2025). "In healthy individuals, insulin is secreted by β-cells in response to hyperglycaemia, promoting glucose uptake and storage." (PMID 40718205, 2025). "On the other hand, isolated post-load hyperglycemia indicates impaired glucose tolerance (IGT) and has been associated with defects in the early and late phases of insulin secretion." (PMID 40569563, 2025). "Exogenous insulin delivery is a potent treatment for severe hyperglycemia or when satisfactory regulation of blood sugar levels cannot be achieved despite the use of different oral hypoglycemic drugs." (PMID 39815320, 2025). "Upregulation of insulin mRNA translation upon hyperglycemia in pancreatic islet β-cells involves several RNA-binding proteins." (PMID 40355555, 2025). "Studies have suggested that the effects of chronic hyperglycemia extend beyond peripheral glucose regulation and involve the role of insulin in the central nervous system." (PMID 40002752, 2025).
Hyperglycemia (continued). "Elevated blood sugar, or hyperglycemia, is a metabolic disorder stemming from abnormalities in insulin production, insulin action, or both." (PMID 39854291, 2025). "Research has indicated that silencing Gpt2 in diabetic livers can mitigate hyperglycemia by reducing amino acid gluconeogenesis and that insulin can suppress the expression of Gpt2 and other gluconeogenic genes." (PMID 40458826, 2025). "By inhibiting the degradation of incretins, these agents enhance insulin secretion, suppress glucagon release, and reduce postprandial hyperglycemia-dependent oxidative stress, thereby attenuating AGE accumulation and glomerular endothelial dysfunction." (PMID 40534883, 2025). "Coherently, insulin secretion-related indices improved by applying the HIF-1α inhibitor PX-478 to human islet organoids exposed to hyperglycemia." (PMID 40926989, 2025). "GLP-1 receptor agonists delay gastric emptying, suppress glucagon secretion, and can reduce postprandial hyperglycemia, offering the potential to further optimize glucose control beyond what insulin-only closed-loop systems can achieve." (PMID 40231429, 2025). "It is suggested to consider a fixed dose of intermediate‐ or long‐acting insulin alongside intravenous insulin infusion to manage glucocorticoid‐induced hyperglycemia." (PMID 40931439, 2025). "Homeostasis of the glucose concentration is achieved by an adequate release of insulin in response to a metabolic demand (hyperglycemia) of the organism." (PMID 40243540, 2025). "The patient required inpatient care to treat hyperglycemia and refractory hypokalemia with insulin infusion and IV potassium replacement, respectively." (PMID 40270995, 2025). "TZDs, a class of full PPARγ agonists, increase insulin sensitivity in peripheral tissues and help reduce hyperglycemia." (PMID 40149950, 2025). "An increase in blood flow improves the delivery of insulin and glucose to cells, increasing their uptake and possibly reducing hyperglycemia." (PMID 41214779, 2025). "In proband 2, the hyperglycaemia was transient, requiring insulin treatment until the age of 5 weeks." (PMID 40062559, 2025). "GCK-hyperglycemia patients received a higher total daily dose of insulin during the first trimester than HNF1A-MD patients (0.54 ± 0.14 vs. 0.41 ± 0.17 units/kg, p=0.041)." (PMID 41409604, 2025). "Prolonged UPR activation results in apoptosis of β-cells through the PERK-eIF2α-CHOP pathway, contributing to reduced insulin secretion and worsening hyperglycemia." (PMID 40563357, 2025). "In 1952, Jørgen Pedersen proposed that maternal hyperglycemia leads to increased transplacental glucose transfer, which stimulates excessive insulin production by the fetal pancreatic β-cells." (PMID 40807035, 2025). "For example, ERO1β overexpression significantly increased ER hydrogen peroxide content and led to impaired insulin secretion and hyperglycemia in a mouse model." (PMID 40136648, 2025). "Nutritional status also modulates insulin sensitivity, as malnutrition reduces muscle mass (a primary site for insulin-mediated glucose uptake) while corticosteroid use during exacerbations induces transient hyperglycemia." (PMID 40842499, 2025). "The treatment of glucocorticoid-induced hyperglycemia relies on insulin administration depending on the type and duration of action of glucocorticoid therapy." (PMID 40284576, 2025). "Before pregnancy diet therapy predominated in GCK-hyperglycemia (56.0% vs 0%, p<0.001), while insulin therapy was more frequent in HNF1A-MD (67.0% vs. 17.0%, p=0.006)." (PMID 41409604, 2025). "It is noteworthy that the POMC-Cre ERt2:: FASNflox/flox mice also secreted significantly less insulin in response to hyperglycemia as early as 15 min after infusion started." (PMID 40541585, 2025). "Hyperglycemia is the hallmark of T2DM, a metabolic disorder that is caused by deficiencies in either insulin secretion or activity, or perhaps both." (PMID 40548446, 2025).
Hyperglycemia (continued). "First, the role of SGLT2i in modulating insulin sensitivity and reducing hyperglycemia is well‐established." (PMID 40289065, 2025). "Oltipraz ameliorates hyperglycemia and pancreatic damage through Nrf2/HO‐1 axis activation, concurrently improving lipid metabolism and insulin secretion capacity." (PMID 40599237, 2025). "Latest hybrid closed‐loop systems aim to minimise hypoglycaemia and hyperglycaemia and maintain glucose levels within a target range through use of a computerised algorithm to adjust the basal rate of insulin and administer corrective bolus doses." (PMID 39432570, 2025). "In this study, glycerol-based intervention induced hyperglycemia to stimulate pancreatic β-cell insulin secretion." (PMID 40805081, 2025). "Similar levels of anti-insulin antibodies and comparably rapid induction of hyperglycemia upon anti–PD-L1 or anti–PD-1 treatment indicated that both NOD βST and littermate mice contained β cell–reactive B and T cells." (PMID 40759576, 2025). "Early glargine administration can decrease morbidity from rebound hyperglycemia and reduce the cost of care by minimizing the amount of time required to be on an insulin drip in a critical care setting." (PMID 40978981, 2025). "Intravenous insulin infusions are preferred in intensive care settings, particularly for patients with persistent glucose > 180 mg/dL, to rapidly correct hyperglycemia and maintain stable glucose levels." (PMID 40868089, 2025). "Acute pancreatitis usually presents with transient hyperglycemia and rarely requires long-term insulin treatment." (PMID 40901503, 2025). "DM is a heterogeneous metabolic disorder characterized by hyperglycemia resulting from defects in insulin secretion and/or insulin action." (PMID 41474783, 2025). "Glucotoxicity exacerbates hyperglycemia by impairing insulin secretion and sensitivity, necessitating effective interventions." (PMID 40828947, 2025). "Taken together, these results suggest that hexanoic acid is a potent FFA which improves hyperglycemia under HFD feeding by enhancing insulin sensitivity." (PMID 40944255, 2025). "In insulin-resistant states, the normal action of insulin on glucose uptake and metabolism is impaired, leading to hyperglycemia and subsequent renal damage." (PMID 40698245, 2025). "The findings demonstrated that FCJ and RCJ ameliorated hyperglycemia, dyslipidemia, and abnormal hepatic function; mitigated hepatic lipid accumulation; and restored insulin expression levels." (PMID 40458826, 2025). "This requires close monitoring of blood glucose to adjust insulin dosing and avoid hypoglycemia and hyperglycemia." (PMID 40125239, 2025). "Hepatic IR also leads to increased gluconeogenesis—a process normally suppressed by insulin—resulting in hyperglycaemia." (PMID 40403112, 2025). "Previous reports have indicated that the oral administration of HYA 2 h before OGTT in mice ameliorated postprandial hyperglycemia as well as linoleic acid, depending on the promotion of insulin secretion via GPR40 pathway." (PMID 39899133, 2025). "STZ mainly damages insulin-producing β-cells, leading to the generation of ROS and impaired insulin secretion, all of which contribute to hyperglycemia." (PMID 40867548, 2025). "These guidelines underscore the importance of actively managing hyperglycemia with insulin in patients undergoing intravenous thrombolysis for acute ischemic stroke." (PMID 40538655, 2025). "Clinically, affected infants present shortly after birth or in early infancy with severe hyperglycemia requiring insulin therapy, along with malabsorption and failure to thrive due to absent digestive enzymes." (PMID 41393705, 2025). "The activation of HPA axis dysfunction appears to be bidirectional: hyperglycemia itself stimulates cortisol release, while chronic cortisol exposure worsens β-cell function and insulin sensitivity." (PMID 40869170, 2025).